CD177 (CD177 molecule)
Diseases named in the same sentence as CD177 in open-access papers (continued):
Sharing a sentence is not in itself a finding about the gene and the disease.
tumor (continued). "We further found that CD177 expressed by cancer cells has tumor-suppressive functions via regulating β-catenin activation." (PMID 34599187, 2021). "We have demonstrated that CD177+ tumor-infiltrating Treg cells are hyper-suppressive to effector T cells and anti-CD177 antibody is able to block the suppressive function of CD177+ tumor-infiltrating Treg cells." (PMID 34831009, 2021). "All 3 oncogenes in 50 CRCs, except for MYC in one tumor and CDK4 in three tumors, were upregulated and 3 normal colonic physiological genes were downregulated, except for CD177 in one tumor, AQP8 in two tumors and GPX3 in three tumors." (PMID 31409279, 2019). "Our study identifies CD177+ tumour neutrophil infiltration as an adverse prognostic factor for bevacizumab treatment." (PMID 30377339, 2019). "Therefore, further investigation into the functional gaps and regulatory mechanisms of CD177, particularly its involvement in tumor immunity and inflammatory processes, is imperative." (PMID 41142798, 2025). "Furthermore, CD177 is also expressed on tumor-infiltrating regulatory T cells (Ti Treg) and within tumor tissues, indicating a dual role in influencing the clinical and prognostic values across various cancers." (PMID 41142798, 2025). "In general, the expression of CD177 play a dual role for evaluating the prognosis of various tumors, which may depend on the different functions of CD177-mediated neutrophils, Treg cells, and tumor tissue cells." (PMID 41142798, 2025). "Moreover, CD177 influences the function and homeostasis of tumor-infiltrated Treg cells, as demonstrated by reduced tumor growth and decreased tumor-infiltrated Treg frequency upon Treg-specific deletion of CD177 in mice." (PMID 40041860, 2025). "Given CD177’s structural similarity to uPAR, a mediator of cell adhesion and migration, it may regulate tumour adhesion and invasion in GC." (PMID 41451221, 2025). "The role of CD177 in the tumor microenvironment has also attracted much attention, and it may become as a new indicator to evaluate tumor progression and patient prognosis." (PMID 41142798, 2025). "Tumor-expressed CD177 exerts tumor-suppressive functions by regulating β-catenin activation." (PMID 40041860, 2025). "Similarly, CD177-positive tumours were found to correlate significantly with VM formation, as well as with various tumour characteristics and prognosis." (PMID 38892471, 2024). "More importantly, current research has demonstrated that CD177 could improve the inhibitory function of tumor-infiltrating Treg cells (TC) in the TME." (PMID 37528394, 2023). "CD177 was up-regulated in tumor tissue and correlated with Neutrophil content in this study." (PMID 36401283, 2022). "On the contrary, the CD177 gene is highly expressed in tumor tissues." (PMID 36401283, 2022). "It is also tempting to speculate that the novel interaction identified may be in part responsible for a yet uncharacterized interaction between CAFs and tumor-infiltrating Tregs, which have been shown to selectively express CD177." (PMID 34879110, 2021). "While we did not observe significant alterations within immune populations from non-tumor-bearing mice, Treg-specific Cd177-KO led to a significant decrease of TI Treg cells and some other significant changes of various immune cells within various tissues of tumor-bearing mice." (PMID 34599187, 2021). "A study observed that anti-PD-1 therapy induces hyper-progression with clonal expansion of tumor-infiltrating Treg cells with upregulation of some genes, including CD177 and BCL2L1 in a leukemic patient, the two genes we found to be elevated specifically in tumor-infiltrating Treg cells." (PMID 34831009, 2021). "CD177 is a surface protein and may modulate the immune suppressive function and maintain homeostasis of tumor-infiltrating Treg cells in ccRCC." (PMID 34831009, 2021).
tumor (continued). "We first analysed tumour neutrophil infiltrates by immunostaining of CD177+ cells on TMAs derived from colorectal metastasis samples, including samples from lymph node (n = 23 ctx only group; n = 20 bev group), lung or liver (n = 16 ctx only group; n = 26 bev group) metastases." (PMID 30377339, 2019). "Likewise, CD177 staining, which indicates neutrophil infiltration within tissue, was predominately observed in tumor foci but was barely detectable in PCT or normal prostate tissue (p < 0.05)." (PMID 31500632, 2019). "Tumour CD177+ neutrophil infiltration was correlated to clinical outcome." (PMID 30377339, 2019). "Notably, CD177 encodes a neutrophil surface glycoprotein involved in innate immune activation, while NQO2 is associated with redox homeostasis, both of which are crucial in the inflammatory tumor microenvironment." (PMID 41373777, 2025). "However, no Fut4 expression which encodes CD15 or Cd177 was detected in our datasets indicating of lack of capture of neutrophils in our scRNA Seq analysis likely due to their fragility during the tumor isolation process." (PMID 38802355, 2024). "Proteins associated with tumor progression or a bad prognosis such as WNT5A, MMP13, MMP3, telomerase, and NOTCH3 were upregulated while proteins associated with immune cell infiltration or pathway inhibitors/tumor suppressors such as FRZB, CD177, PPARG, and HRASLS2 were downregulated." (PMID 38504345, 2024). "In addition, CD177 deficiency promotes the inflammatory response, proliferation, and tissue remodeling of colonic epithelial cells, which might enlarge tumor size and increase tumor formation in CD177-/- mice." (PMID 37528394, 2023). "In addition, blocking CD177 with antibodies in CD177 + tumor-infiltrating cells may be a novel target for antitumor immunotherapy." (PMID 37528394, 2023). "However, the prognosis was relatively better after its high expression, which may be related to the activation of Neutrophils promoted by CD177, and the content of neutrophils is higher in tumor tissue." (PMID 36401283, 2022). "In light of our results, it is tempting to speculate that modulation the PDPN/CLEC-2/CD177 axis may represent an alternative approach to remove obstacles for T cell entry into tumor beds, by lessening CAF contractility and ultimately decreasing tissue stiffness." (PMID 34879110, 2021). "The CD177-positive neutrophil score was predictive of survival, regardless of whether this count was conducted early on lymph node biopsies at the time of primary tumour resection or later during tumour progression in lung or liver metastases." (PMID 30377339, 2019). "CD177, i.e., a GPI-anchored cell surface glycoprotein functions in neutrophil transmigration and tumor-infiltrating regulatory T cells." (PMID 38245882, 2024). "The co-expression of Npg, Cd177 and Cybb in the SCLL Ly6g + and Camk1d + neutrophils suggested that they are closely related, which is consistent with both being increased in tumor bearing mice." (PMID 38730491, 2024). "The HPA database showed that proteins (CD177, LGALS2, TMC8, and VWA5A) were significantly dysregulated in tumor tissue relative to normal samples." (PMID 37528394, 2023). "Tumor malignant phenotype related IGFBP2 and KRT18 were significantly enriched in KRAS-Mut subtype, whereas neutrophils and macrophages related CD177, MMP1 and ARG1 were enriched in WT subtypes." (PMID 35836817, 2022). "TANs have N1 (anti-tumor) and N2 (tumor-promoting) phenotypes: N1-TANs are marked by CD11b+Ly6G+CD54+CD16+CD170low and CD177+ in mice; However, N2-TANs is characterized by CD11b+Ly6G+PD-L1+CD170high." (PMID 35585567, 2022). "Among the genes co-expressed with CD177 is phosphodiesterase (PDE) 4D, which is an enzyme involved in multiple tumor-related pathways." (PMID 33022971, 2020). "CD177 and AQP8 were downregulated in all 79 CRCs while GPX3, a “tumor suppressor”, was downregulated in 75 out of 79 CRCs (log2T/N < 0)." (PMID 31409279, 2019).
tumor (continued). "For example, PYY, CD177, PEG3, and FAM83D, were observed in more than 11 normal samples, while less than 3 were observed in tumor samples." (PMID 30538721, 2018). "Therefore, the up-regulation of Cd177 observed in this study was considered to be caused not by increased infiltration of neutrophils into the gastric mucosa but by a change of gene expression in tumor cells." (PMID 23899160, 2013). "PECAM-1 mediates the migration of neutrophils and tumor cells, which can be independent of CD177, while CD177 enhances the migration ability of neutrophils and Treg cells and plays a synergistic role." (PMID 41142798, 2025). "Patients with CD177-positive tumours exhibited shorter survival outcomes compared to those with CD177-negative tumours." (PMID 38892471, 2024). "Similar to the human CD177+ TI Treg cells, we found that Treg cells from tumor-bearing WT mice exhibited a stronger suppressive capacity against both CD4+ and CD8+ T cells compared to Treg cells from tumor-bearing Cd177-KO mice." (PMID 34599187, 2021). "To determine the influence of Treg-specific KO of Cd177, we performed a thorough immune profiling from different tissues of normal (non-tumor bearing) or tumor-bearing mice using flow cytometry (gating strategy for lymphocytes)." (PMID 34599187, 2021). "LCN2 levels showed a similar pattern as CD177 staining, significantly higher in tumor foci than PCT and normal tissue (p < 0.001), although it was expressed not only in prostate stroma but also in epithelial cells in tumor foci (Orange)." (PMID 31500632, 2019). "Although they failed to quantify neutrophils in tumor tissues, and there is no direct evidence that CD177 expression is only derived from infiltrating neutrophils in tumor tissues, it may also be expressed on other immune cells (such as Treg cells)." (PMID 41142798, 2025). "In this scenario, increased CD177+ and CLEC-2+ immune cell infiltration could ameliorate PDPN functions, leading to reduced CAF contractility and possibly altering their activation state, ultimately hampering CAF-mediated enhancement of tumor growth." (PMID 34879110, 2021). "We found that CD68 (macrophage), but not CD177 (neutrophil), is positively correlated with CD40 in both normal (r = 0.42) and tumor (r = 0.38) tissues." (PMID 34758832, 2021).
cancer (204 papers, 2004 to 2026). A tumor composed of atypical neoplastic, often pleomorphic cells that invade other tissues. "Similar observations have been reported for other genes such as CXCL11, Plk1, and CD177, where high expression levels are unexpectedly associated with better clinical outcomes in specific cancer types." (PMID 38890197, 2024). "Expression of CD37, a member of the tetraspanin family, has been involved in metastasis, while nothing is known about the possible role in cancer of CD177, a glycosyl-phosphatidylinositol (GPI)-linked surface protein, normally secreted by neutrophils." (PMID 22253825, 2012). "The defensin family genes (DEFA1, DEFA1B, DEFA3) and CD177, typically linked to neutrophil function, may indicate the involvement of innate immunity in cancer development." (PMID 40227838, 2025). "CD177 are considered to have an important role in affecting the clinical and prognostic value of various cancers." (PMID 41142798, 2025). "CD177 is considered to have an important role in affecting the clinical and prognostic value of various cancers." (PMID 37528394, 2023). "Germline KO of Cd177 has minimal phenotype in neutrophils even under bacterial infections, which, on one hand, indicates the safety of blocking CD177 signal; on the other hand, suggests CD177+ TI neutrophil lineage is specific under the cancer context." (PMID 34599187, 2021). "Developing an anti-CD177 blocking antibody, but not a depleting antibody, has the potential to inhibit the suppressive activity of CD177+ TI Treg cells as a complementary method for current cancer immunotherapy." (PMID 34599187, 2021). "CD177 is a surface protein that can be targeted by an antibody-based approach for cancer immunotherapy." (PMID 34599187, 2021). "In addition, low CD177 expression was observed in six patient cancer tissues from the protein level, while normal tissues had relatively high CD177 expression." (PMID 37528394, 2023). "Similarly, for the transcriptomics data we found CXCL8 and CD177 to be altered by metformin where the former has been shown to be altered in healthy individuals and cancer patients." (PMID 36593394, 2023). "Our data thus support that CD177 is specifically expressed within a specific population of TI Treg cells of solid cancers, and that CD177 is able to mediate the suppressive activity of TI Treg cells in cancer." (PMID 34599187, 2021). "One important question is the “targetability” of CD177 for cancer immunotherapy." (PMID 34599187, 2021). "Specific surface markers proposed to identify neutrophil subsets in cancer include CD101 and CD177, which are associated with cancer regression, and CD117, PDL1, CD170, LOX1, CD84 and JAML, which are associated with T cell immunosuppression and cancer progression." (PMID 34674757, 2021). "Recently reported, CD177 can regulate PDPN and thus affect the physiological changes of cancer-related fibroblasts, which seems to be a new therapeutic target." (PMID 36401283, 2022). "Among these proteins, we have identified many differentially abundant proteins identified as having a role in cancer (IFIT1, FASTKD2, PIP4K2B, ARID1B, SLC25A33: overexpressed in TR; CALD1, CPA3, B3GALT5, CD177, RIPK1: overexpressed in NR)." (PMID 29681787, 2018). "We did observe CD177+ Treg cells within the normal liver and transitional/junctional zones of HCC from the single cell data, as well as CD177+ Treg cells from human splenocytes of cancer patients." (PMID 34599187, 2021). "We have identified many differentially abundant proteins already identified as having a role in cancer, such as the earlier discussed proteins IFIT1, FASTKD2, PIP4K2B, ARID1B and SLC25A33 (more abundant in TR) or CALD1, CPA3, B3GALT5, CD177 and RIPK1 (more abundant in NR)." (PMID 29681787, 2018). "Cancer cells of signet-ring cell type (2 cases) were negative for CD177." (PMID 23899160, 2013).
infection (102 papers, 2004 to 2025). The state of being infected such as from the introduction of a foreign agent such as serum, vaccine, antigenic substance or organism. "A greater than 5-fold upregulation was observed in transcripts of Chil1, encoding a chitinase-3-like glycoprotein involved in modulating infection and inflammation and CD177, encoding a glycosylphosphatidylinositol-linked cell surface antigen mediating neutrophil proliferation." (PMID 35311902, 2022). "In peripheral blood, CD177 is exclusively expressed on neutrophils that serve as the first line of defense against infections and the primary mediator for inflammation." (PMID 39131159, 2024). "In the healed group (n = 17), CD177 was highly expressed in response to active infection at 0 weeks and became downregulated at 8 weeks following antibiotic therapy." (PMID 37434783, 2023). "CD177, which is thought to be expressed exclusively on PMNs and upregulated during infection, has also been demonstrated to mediate PMN-endothelial cell interaction to promote PMN transmigration by binding platelet endothelial cell adhesion molecule-1." (PMID 34944086, 2021). "CD177 was selected as a representative gene of neutrophil activation state because CD177 is a neutrophil-specific marker 36 and importantly, it was the most highly differentially expressed gene in severe infection." (PMID 31366921, 2019). "This population includes several neutrophil-associated genes (OLFM4, CD177, SERPINB1, S100P, PTX3 and MMP8), suggesting that there is an accumulation of neutrophils in PBCMs during the course of infection." (PMID 27595844, 2016). "We investigated the alteration of CRP, WBC, neutrophil count, suPAR levels, CD4+ CD25high Tregs, CD64+ and CD177+ neutrophils and monocytes in 12 acute ischemic stroke patients free of infection within 6 hours and one week after the insult." (PMID 24597828, 2014). "We further confirmed enhanced CD177 expression in murine neutrophils following infection." (PMID 38517968, 2024). "CD177 expression is the most dysregulated in sepsis patients, indicating a role in infection." (PMID 39131159, 2024). "Importantly, certain infections lead to an upregulation of CD177 on human neutrophils, leading to potentially prolonged neutrophil survival for efficient clearance of the bacteria." (PMID 25359465, 2015). "We speculate that that interaction between CD177 of myeloid progenitor cells and IgG immune complexes may provide a stimulatory signal to drive promyeloid cell proliferation and differentiation into mature neutrophils during infections and diseases." (PMID 39131159, 2024). "This suggests that the observed increases in CD177 expression could be induced by peripheral priming, rather than being mainly attributable to infection-associated mobilization of bone marrow neutrophil pools." (PMID 38517968, 2024). "As infection progressed, we detected a robust upregulation of genes encoding cytokines and chemokines (CCL2, CCL3, IL1B, CXCR1, IL1RN) as well as granulocyte associated transcripts (TLRs 1-4, SPI1, S100A8, S100A9, CD177), which correlated with the higher numbers of granulocytes 5 DPI." (PMID 28852031, 2017). "Parallel to upregulation of core histones, the CD177 gene (a neutrophil-specific marker), MYBL2 and RRM2 were highly expressed during the active phase of infection (0 weeks) and the expressed genes were reduced at 8 weeks after therapy." (PMID 37434783, 2023). "CD177 and RRM2 were also upregulated at the initial phase of active infection (0 weeks) compared with that at 8 weeks of follow-up." (PMID 37434783, 2023). "Notably, a new cluster-4 population not only expressed Cd177 but also enriched Stefins A (Stfa) family genes (Stfa1, Stfa2, Stfa3, Stfa2l1, and BC100530) upon infection." (PMID 35420442, 2022). "The trend was maintained at three days after infection, but the difference was not statistically significant between infected WT or CD177−/− mice." (PMID 25359465, 2015).